NRP1 (neuropilin 1)
Diseases named in the same sentence as NRP1 in open-access papers (continued):
Sharing a sentence is not in itself a finding about the gene and the disease.
melanoma (continued). "Moreover, we reported that NRP1 expression is markedly upregulated in BRAF-inhibitor-resistant melanoma cells; however, the mechanism triggering NRP1 activity was not elucidated." (PMID 32784465, 2020). "In this respect, VEGF-dependent neuropilin signaling has been reported to play a relevant role in cancer; however, we have previously shown that VEGF is unlikely to be implicated in establishing NRP1-dependent melanoma resistance to BRAF inhibitors." (PMID 32784465, 2020). "NRP-1 overexpression was also detected in some tumor cells such as breast, prostate, and melanoma cells, which indicates using a NRP-1-specific moiety could lead to both tumor cell and tumor vasculature targeting." (PMID 33568892, 2019). "Indeed, our in vivo experiments have revealed that, like the anti-PD-1 blockade, anti-Nrp-1 immunotherapy is able to inhibit melanoma progression in C57BL/6 mice." (PMID 31350404, 2019). "In NRP-1 proficient melanomas, microenvironmentally- or tumour-secreted PDGF-C may activate specific signal transduction pathways (including p130Cas phosphorylation) and transcription factors (like Snail), which promote an invasive phenotype." (PMID 28977999, 2017). "Moreover, PDGF-C silencing significantly down-modulates the expression of Snail, a transcription factor involved in tumour invasiveness that is highly expressed in NRP-1 positive melanoma cells." (PMID 28977999, 2017). "Overall, these results strengthen the hypothesis that the PDGF-C/NRP-1 autocrine loop may contribute to the maintenance of an aggressive phenotype in melanoma cells." (PMID 28977999, 2017). "Moreover, in vitro and in vivo studies performed by our group and other authors have demonstrated that NRP-1 is involved in melanoma invasiveness." (PMID 28977999, 2017). "The high PDGF-C homology to VEGF-A prompted us to investigate whether this growth factor may also interact with the VEGF-A co-receptor NRP-1 and co-operate with it in promoting melanoma aggressiveness." (PMID 28977999, 2017). "Furthermore, high NRP1 expression was observed in 67% of melanomas with a thickness >2.00 mm, compared with 49% of tumors with a thickness ≤2.00 mm (P=0.004)." (PMID 25954957, 2015). "Furthermore, χ2 test revealed that the percentage of high NRP1 staining was significantly greater in primary melanoma (56%) and metastatic melanoma (62%), compared with that in common nevi (11%) and dysplastic nevi (24%) (P=3.6×10−9, CN+DN vs. PM+MM)." (PMID 25954957, 2015). "Furthermore, multivariate Cox proportional hazard analysis also indicated that NRP1 expression is an independent prognostic marker for melanoma." (PMID 25954957, 2015). "If confirmed in NRP-1 expressing melanoma cells, this pathway might also contribute to tumor aggressiveness." (PMID 26090340, 2015). "Moreover, NRP-1 over-expression provides human melanoma cells with an increased in vivo growth rate." (PMID 26090340, 2015). "Although over-expressed in melanoma, NRP-1 has a widespread expression in normal adult tissues." (PMID 26090340, 2015). "This evidence supports the hypothesis that NRP-1 might represent a suitable target for anti-melanoma therapies." (PMID 26090340, 2015). "The current study also examined whether NRP1 expression is an independent prognostic marker for survival of patients with melanoma patients, using multivariate Cox proportional hazard analysis." (PMID 25954957, 2015). "In melanoma cells, NRP-1 has been shown to activate signal transduction pathways involving AKT." (PMID 26090340, 2015). "Notably, high NRP1 expression was correlated with a poorer 5-year and 10-year survival in patients with melanoma, and was shown to be an independent prognostic factor." (PMID 25954957, 2015). "In addition, the correlation between matrix metalloproteinase 2 (MMP2) and NRP1 expression in patients with melanoma was analyzed." (PMID 25954957, 2015). "The presence of NRP-1 and integrins correlates with a more aggressive melanoma." (PMID 26558271, 2015).
melanoma (continued). "Accordingly, T cell-specific ablation of NRP-1 resulted in compromised melanoma growth." (PMID 23185562, 2012). "In the present study, we have, thus, investigated if other extracellular signals might trigger NRP1-dependent tumor malignancy, and found that a relatively poorly studied NRP1-ligand, Galectin-1 (Gal-1), is upregulated in melanoma cells upon the onset of resistance to BRAF-targeted drugs." (PMID 32784465, 2020). "Based on PDGF-C higher structural homology to VEGF-A than to other PDGF family members and on VEGF-A ability to stimulate NRP-1, we have investigated whether PDGF-C activates NRP-1 and cooperates with it in melanoma progression, likely favouring the metastatic switch." (PMID 28977999, 2017). "In conclusion, our results demonstrate for the first time a direct activation of NRP-1 by PDGF-C and strongly suggest that autocrine and/or paracrine stimulation of NRP-1 by PDGF-C might contribute to the acquisition of a metastatic phenotype by melanoma cells." (PMID 28977999, 2017). "Thus, inhibition of NRP-1 may prevent the activation of compensatory mechanisms that stimulate melanoma cell proliferation and limit the efficacy of BRAF inhibitors." (PMID 26090340, 2015). "Kruskal-Wallis test on the NRP1 scoring pattern in the patient samples revealed that NRP1 expression increased significantly from common nevi (mean 3.1) and dysplastic nevi (mean 4.2), to primary melanoma (mean 6.7) and metastatic melanoma (mean 70; P<0.0001, CN+DN vs. PM+MM)." (PMID 25954957, 2015). "However, the function of NRP1 in melanoma progression, as well as the effect of NRP1 expression on the prognosis of patients with melanoma remains unknown." (PMID 25954957, 2015). "NRP-1 might be also involved in the effects of PlGF on melanoma cells." (PMID 26090340, 2015). "Moreover, NRP-1-dependent pathways described in endothelial cells or other tumor models might be active in melanoma and contribute to BRAF inhibitor resistance." (PMID 26090340, 2015). "Neuropilin-1 (NRP1), a co-receptor of VEGF found in melanoma and SCC tumor cells, mediates the role of VEGF in maintaining CSC self-renewal." (PMID 40399946, 2025). "Other immune checkpoint protein such as NRP1 is found in non-small cell lung cancer (NSCLC)- and melanoma-derived exosomes." (PMID 40908470, 2025). "Melanoma cells express two PIGF isoforms, namely PlGF-1 and PlGF-2, which bind to neuropilin-1 and neuropilin-2 receptors on ECs." (PMID 39866233, 2025). "The deletion of NRP1 and/or NRP2 specifically in ECs profoundly hampers melanoma progression and disrupts the angiogenic processes crucial for tumor vascularization." (PMID 40399946, 2025). "A recent study also revealed that melanoma-derived exosomes preferentially encapsulate NRP1 to enhance the recruitment of PD1 + and NRP1 + Tregs to TME, thereby promoting tumor growth." (PMID 40908470, 2025). "However, whether NRP1 affects IFNγ signaling in melanoma cells is unknown." (PMID 39736644, 2024). "Neuropilin 1 (Nrp1)−/− Tregs in mice with a partial Nrp1 knockout can prevent wild-type (Nrp1+/+) Tregs from performing their immunosuppressive function by secreting IFN-γ, thus promoting the clearance of melanoma." (PMID 38807592, 2024). "Next, we studied the binding of WT and RPAR-coated CF555-labeled TBSV NPs to cultured NRP-1-positive PPC-1 prostate cancer cells and NRP-1-negative M21 melanoma cells." (PMID 37111013, 2023). "A number of identified molecules, including TNFRSF13B, LAG3, NRP1, ENTPD1, NT5E, CCL21, and CCR7, can serve as future therapeutic targets in the treatment of melanoma." (PMID 34159752, 2021). "A number of identified molecules including TNFRSF13B, LAG3, NRP1, ENTPD1, NT5E, CCL21, and CCR7 can serve as future therapeutic targets in melanoma treatment." (PMID 34159752, 2021). "Mechanistically, Gal-1 sustains increased expression of NRP1 and EGFR in drug-resistant melanoma cells." (PMID 32784465, 2020).
melanoma (continued). "NRP1 was previously shown to mediate EGFR upregulation, driving resistance to targeted therapies, such as those inhibiting BRAF in melanoma cells." (PMID 32784465, 2020). "To investigate the impact of Nrp-1 engagement with its ligand on CD8+ TIL functions in vivo, we used C57BL/6 mice engrafted with B16F10 melanoma cells, which express the Nrp-1 soluble ligand Sema-3B, as shown by qRT-PCR analyses and confirmed by western blot." (PMID 31350404, 2019). "While transcription of NRP1 in melanoma cells is barely detectable due to the action of SOX10/miR-338, this downregulation loses its effect in response to targeted therapy, allowing for NRP1 upregulation and drug resistance formation." (PMID 30717262, 2019). "Another important member in the αv family is integrin αvβ5, which is important for neuropilin 1 (NRP-1)-dependent angiogenesis and tumor aggressiveness in melanoma." (PMID 29703238, 2018). "This study provides evidence that in human melanoma cells expressing NRP-1 but devoid of other VEGFRs and PDGFRα expression, an autocrine PDGF-C/NRP-1 loop sustains several characteristics of melanoma aggressive phenotype." (PMID 28977999, 2017). "Neuropilin-1 (NRP-1), a co-receptor for vascular endothelial growth factor-A (VEGF-A) tyrosine kinase receptors (VEGFRs), has been suggested to play a relevant role in melanoma progression." (PMID 28977999, 2017). "Subsequent studies in human tissue demonstrated that Treg cells in peripheral blood, and within melanoma and HNSCC tissue samples, express Nrp1, which correlated with poor prognosis." (PMID 28716068, 2017). "However, the significance of NRP1 in melanoma progression, diagnosis and prognosis remains unknown." (PMID 25954957, 2015). "NRP-1 enhances the activation of a VEGF-A/VEGFR-2 autocrine loop, which promotes the invasion of melanoma cells into the extracellular matrix, through the up-regulation of VEGF-A and metalloproteinases secretion." (PMID 26090340, 2015). "We report that Nrp1 was selectively induced and highly expressed on CD8+ T cells engaging self-antigen, both in mice and in human melanoma infiltrating T cells." (PMID 25343644, 2014). "In evaluations of Nrp1 on human CD8+ T cells, we observed that some melanoma tumor-infiltrating T cells displayed significantly upregulated Nrp1 relative to T cells from normal adjacent skin tissue or peripheral blood." (PMID 25343644, 2014). "NRP1 is a transmembrane glycoprotein that has been shown to affect IFNγ signaling in endothelial cells, and is furthermore negatively regulated by MITF in melanoma cells." (PMID 39736644, 2024). "The researchers used melanoma cell clones M14-N, expressing NRP-1 but lacking VEGFR-1, and M14-C, devoid of both receptors." (PMID 38791873, 2024). "Focal adhesion, melanoma, and GAP junction were differentially enriched in phenotypes with high NRP1 expression, while Peroxisome proliferator-activated receptor (PPAR) signaling and multiple metabolism-related pathways were significantly enriched in low NRP1 expression phenotypes." (PMID 34249735, 2021). "Since VEGFR2 is not expressed at significant levels in melanoma cells, we posited that NRP1 elicits a distinct signaling pathway upon Gal-1 engagement in this context." (PMID 32784465, 2020). "Third, Gal-1 knock-down did not impact the viability of drug-sensitive melanoma cells, which express negligible levels of NRP1." (PMID 32784465, 2020). "It was previously reported that NRP1 negatively controls the expression of p27/Kip1 cyclin-dependent kinase inhibitor in cancer cells, a mechanism required to unleash the pathway leading to EGFR upregulation in PLX-resistant melanoma cells." (PMID 32784465, 2020). "Conversely, Gal-1 overexpression could trigger this signaling circuit, promoting the upregulation of NRP1 and that of its downstream target EGFR in parental melanoma cells." (PMID 32784465, 2020).
melanoma (continued). "The absence of NRP-1 in CD4+ T cells led to the activation of an anti-tumor immune response in melanoma-bearing mice, as evidenced by an increase in CD8+ T cells and a decrease in Tregs within the TME." (PMID 33266104, 2020). "Similarly, interaction of VEGF with NRP1 expressed on Tregs was found critical for tumor homing, since by abolishing NRP1 expression Tregs populations were reduced, resulting in CD8+ T-cells raise in melanoma mouse models." (PMID 33121034, 2020). "Moreover, at day 14 after melanoma cell transplantation, tumours from vaccinated mice showed increased absolute numbers of CD8+ TIL expressing PD-1, Nrp-1 and Tim-3 and, to a lesser extent, CTLA-4 and LAG-3." (PMID 31350404, 2019). "Similar to miR-338 in melanoma cells, in medulloblastoma cells, miR148a and in non-small cell lung cancer, miR-152 inhibits the translation of NRP1, while in cholangiocarcinoma, miR320 negatively regulates NRP1 expression." (PMID 30717262, 2019). "In a competitive setting, we investigated the long-term persistence and recall activity of Nrp1–/– and Nrp1+/+ pMel-T cells (transgenic CD8+ T cells expressing TCR specific for gp100 melanoma antigen) in response to gp100-B16 tumors, after co-transferred into the same host." (PMID 30400822, 2018). "Moreover, we previously reported that human melanoma cells, which co-express high PDGF-C and NRP-1 levels, show a marked invasive behaviour suggesting a relevant role for both molecules in the promotion of melanoma aggressiveness." (PMID 28977999, 2017). "In the present study, we demonstrate for the first time that PDGF-C, in the absence of PDFGRα, is able to bind NRP-1 and that this interaction contributes to the aggressive phenotype of melanoma cells by activation of specific signal transduction pathways." (PMID 28977999, 2017). "In melanoma cells expressing NRP-1 but lacking PDGFRα, PDGF-C stimulates extra-cellular matrix (ECM) invasion and induces p130Cas phosphorylation." (PMID 28977999, 2017). "NRP-1 expression has been correlated with melanoma metastatic potential and our findings on its activation by PDGF-C suggest that a PDGF-C/NRP-1 autocrine loop might sustain, at least in part, the aggressive phenotype of NRP-1 positive melanoma cells." (PMID 28977999, 2017). "Indeed, melanoma cell exposure to PDGF-C results in increased p130Cas phosphorylation, which is a downstream effector of NRP-1." (PMID 28977999, 2017). "To investigate whether abrogation of Nrp-1 inhibited tumor growth by suppressing angiogenesis, we used an anti-CD31 antibody to stain melanoma tumor sections." (PMID 27075020, 2016). "In particular, in the absence of VEGFR-1/2, NRP-1 promotes melanoma invasiveness, through the activation of selected integrins, by stimulating VEGF-A and metalloproteinases secretion and modulating specific signal transduction pathways." (PMID 26090340, 2015). "Therefore, the present study further examined the correlation between NRP1 and MMP2 expression in melanoma biopsies, and analyzed the combined effect of NRP1 and MMP2 expression in predicting patient outcomes." (PMID 25954957, 2015). "Based on this results, it is hypothesized that a powerful cell survival regulator, such as NRP1, may be a positive regulator of MMP2, and therefore promote melanoma progression, invasion and metastasis." (PMID 25954957, 2015). "Besides being found in vascular and lymphatic channels, NRP1 and NRP2 are also expressed in a wide variety of human cancers, such as lung, breast, prostate, colon, pancreas, neuroblastoma, melanoma, etc.." (PMID 25890345, 2015). "Furthermore, there was a significant positive correlation between NRP1 and MMP2 expression in melanoma biopsies, and their concomitant expression was inversely correlated with the survival of patients with melanoma." (PMID 25954957, 2015).
melanoma (continued). "On the one hand, an increase in the NRP-1 phenotype induces the production of IFN-γ in the tumor, which increases the vulnerability of Tregs, weakens tumor immunosuppression, and enhances antitumor immunity, which is related to the prognosis of melanoma and head and neck squamous cell carcinoma." (PMID 38807592, 2024). "Indeed, specific deletion of Nrp-1 in Treg cells (Nrp1f/fFoxp3Cre mice) or blockade of Nrp-1 with Sema4a mAb, Nrp-1 mAb and Sema4a-Ig significantly decreased tumor growth in the B16F10 melanoma mouse model." (PMID 34539668, 2021). "Since multidrug therapeutic regimens have shown a reduced risk of non-specific adverse effects, the strong efficacy of NRP1/Gal-1 combined targeting offers a promising perspective for regaining therapeutic efficacy for BRAF inhibitors in melanomas that have developed drug-resistance." (PMID 32784465, 2020). "Although the peptidomimetic NRP1 inhibitor EG00229 could rescue responsiveness to BRAF-targeted therapy in resistant melanoma cells, drug resensitization was never complete." (PMID 32784465, 2020). "First, the knock-down of either Gal-1 or NRP1 showed the same functional impact on restoring drug sensitivity in melanoma cells; moreover, the effects of these treatments were not additive and were instead mutually exclusive, suggesting that the targeted effectors lie in the same signaling pathway." (PMID 32784465, 2020). "However, the potential role of extracellular ligands eliciting NRP1 activity in drug-resistant melanoma cells was not elucidated." (PMID 32784465, 2020). "Notably, semaphorin-NRP1 signaling is not involved in sustaining cell viability, and we have previously shown that VEGF-NRP1 autocrine signaling is not implicated in the pathway leading to EGFR upregulation and drug resistance in melanoma cells." (PMID 32784465, 2020). "M21 melanoma cells that do not express NRP-1 were also included in the assay." (PMID 32497513, 2020). "Independent of VEGFR1, PlGF promotes invasion and VM in melanoma via NRP1." (PMID 30717262, 2019). "Indeed, Nrp-1 was highly induced on CD8+ T lymphocytes engaging self-antigen, including human melanoma TIL, supporting the hypothesis that it may correspond to a potential biomarker for dysfunctional T cells." (PMID 31350404, 2019). "Therefore, based on our findings in different M14-derived clones and other melanoma cell lines expressing NRP-1 and PDGF-C, it can be hypothesized that PDGF-C requires Snail to stimulate ECM invasion and vasculogenic mimicry of melanoma cells." (PMID 28977999, 2017). "Consistently, NRP-1 negative melanoma cells fail to migrate toward the growth factor." (PMID 28977999, 2017). "Thus, targeting NRP-1 would result in decrease of the immune suppressive activity of pDCs and Tregs against melanoma, likely without inducing autoimmunity." (PMID 26090340, 2015). "Since melanoma cells co-expressing high levels of NRP-1 and platelet derived growth factor-C (PDGF-C) show a highly invasive behaviour and PDGF-C shares homology with VEGF-A, in this study we have investigated whether PDGF-C directly interacts with NRP-1 and promotes melanoma aggressiveness." (PMID 28977999, 2017). "Interestingly, melanoma cells expressing NRP-1 but lacking other VEGF-A or PlGF receptors, specifically responded to PlGF in a chemotactic assay, suggesting that PlGF may perform at least some of its functions through activation of NRP-1 dependent pathways." (PMID 26090340, 2015). "In fact, NRP1 expression was basally very low in parental BRAF-addicted melanoma cells A375 and SK-MEL-28, and Gal-1 silencing did not significantly impact NRP1 levels." (PMID 32784465, 2020). "Unlike NRP1, which is more likely to be expressed by carcinomas, NRP2 is rather expressed in neuronal tumors and in melanomas." (PMID 30717262, 2019).